RNU4-39P (RNA, U4 small nuclear 39, pseudogene)
Gene: Small nuclear RNA gene on chromosome 11 (66,614,964 to 66,615,090, reverse strand). Ensembl gene ENSG00000199325.
Homologues: Orthologues: chimpanzee U4 (100% identical), macaque U4 (83% identical), guinea pig U4 (57% identical), rat LOC120096861 (56% identical). Paralogues in human: U4 (66% identical), RNU4-72P (65% identical), RNU4-6P (63% identical), RNU4-82P (63% identical), RNU4-9P (63% identical), RNU4-36P (61% identical), RNU4-48P (61% identical), RNU4-55P (61% identical), U4 (61% identical), RNU4-29P (60% identical), RNU4-91P (60% identical), RNU4-65P (59% identical), and 82 more.